MCL1 (MCL1 apoptosis regulator, BCL2 family member)
Diseases named in the same sentence as MCL1 in open-access papers (continued):
Sharing a sentence is not in itself a finding about the gene and the disease.
breast carcinoma (continued). "A decline in Puma levels did not increase Mcl-1–Mule complex (data not shown) or ubiquitination of Mcl-1 as assessed by immunoprecipitation and western analysis in breast cancer cells." (PMID 21730980, 2011). "However, the apoptotic cell death did not correlate with the levels of MCL1 expression in breast cancer cells, suggesting that AZD4573 induces tumor cell death through another mechanism in breast cancer cells." (PMID 40713627, 2025). "Fourth, we used capivasertib, an AKT inhibitor currently approved for breast cancer treatment, and observed that capivasertib could significantly reduce T163pMcl-1 and Mcl-1 levels without affecting S159pMcl-1." (PMID 40707672, 2025). "Consequently, the dual therapy targeting Mcl-1 and HER2 may be a potential treatment regimen for HER2-overexpression breast cancer." (PMID 37896184, 2023). "Therefore, simultaneous inhibition of MCL-1 and BCL-2 may further inhibit the growth of ER+ breast cancer cells and reverse cell resistance to venetoclax." (PMID 37352173, 2023). "Finally, the TRIP12/FBW7/MCL-1 axis is well preserved in ovarian cancer but not in breast cancer cells since siRNA-mediated depletion of TRIP12 sensitized those cells to Taxol in an FBW7-dependent manner." (PMID 36672454, 2023). "Finally, TRIP12 deletion leads to enhanced mitotic arrest and cell death in an FBW7 and MCL-1 dependent manner in multiple cell lines including colorectal and ovarian cancer but not in breast cancer." (PMID 36672454, 2023). "Also, breast cancer cells are resistant to clinical trial drugs such as the Bcl-2/Bcl-xL inhibitor, ABT-263, which may result from increased Mcl-1 expression." (PMID 37537243, 2023). "In addition, it has been reported that UA induces endoplasmic reticulum (ER) stress and autophagy in MCF-7 human breast cancer cells, and autophagy-dependent endoplasmic reticulum stress protects cells from UA-induced apoptosis through EIF2AK3-mediated MCL1 upregulation." (PMID 37190306, 2023). "MCL-1 abundance is controlled at multiple levels including transcriptional, translational, and post-translational mechanisms, and each of these could be therapeutically targeted to reduce MCL-1 levels in breast cancer." (PMID 35349392, 2022). "PDX models of TNBC have shown that a reversible cell state enriched in a cancer stem-like cell (CSC) gene expression signature arises in drug-refractory breast cancer, and as elevation of MCL-1 occurs in treatment-resistant samples it is tempting to speculate that MCL-1 may facilitate this process." (PMID 35349392, 2022). "However, bCAFs increased Mcl-1 expression in breast cancer cells both at the mRNA and protein level, without affecting Bcl-2 levels." (PMID 35053443, 2022). "Whilst other non-apoptotic roles of MCL-1 could still be important in breast cancer, its function within the BCL-2 family is crucial and can be targeted by MCL-1-specific BH3-mimetic drugs in development for clinical use." (PMID 33785871, 2021). "In the absence of BAK and BAX, genetic deletion of MCL1 has no impact on breast cancer cells." (PMID 34475520, 2021). "Therefore, whilst MCL-1 may be dispensable for bulk MMTV-PyMT cell culture in 2D monolayer, it is essential for growth of breast cancer stem cells in vitro." (PMID 33785871, 2021). "There are compelling data showing that targeting MCL-1 represents a therapeutic opportunity in breast cancer with model systems revealing that breast cancer may be dependent on MCL-1, and that MCL-1 inhibition can enhance the effect of conventional cancer therapies." (PMID 33785871, 2021). "In this study we provide evidence that targeting MCL-1 could have therapeutic impact in established breast cancers and show that the mechanism of breast cancer dependence on MCL-1 is through its canonical anti-apoptotic function that can be targeted by MCL-1-specific BH3-mimetics." (PMID 33785871, 2021).
breast carcinoma (continued). "Based on data demonstrating a difference in the dependence of CAFs on BCL-2 vs. MCL-1 for survival, studies have shown that CAFs in human breast cancer are sensitive to inhibitors targeting MCL-1 (A-1210477 and S63845) but not to those targeting BCL-2/BCL-XL (ABT-737 and navitoclax)." (PMID 33114328, 2020). "In luminal breast cancer cells, we have shown that CAFs conditioned-media-induced apoptotic resistance to BCL-2/BCL-xL inhibitors could be completely reversed with a BH-3 mimetic targeting MCL-1 (A1210477)." (PMID 33080792, 2020). "Therefore, splicing regulation of Mcl-1 and BIM by SRSF1 may contribute to breast cancer cell survival." (PMID 32106418, 2020). "Interestingly, while BIO similarly downregulated BCL-XL in breast cancer cells, it also reduced MCL-1 expression, not via transcriptional control, but through a proteasome-dependent mechanism." (PMID 30679640, 2019). "We report here that mTOR-dependent MCL1 translation rapidly drives Mcl-1 upregulation in ER+ breast cancer cells treated with ABT-263, or with BH3 mimetics that target Bcl-2 alone (ABT-199) or Bcl-xL alone (A1155463), consistent with the well-established oncogenic role of mTOR in ER+ breast cancers." (PMID 31595181, 2019). "We found abundant Mcl-1 expression (but not Bcl-2 or Bcl-xL) upon LTED in cell culture and in vivo, suggesting that Mcl-1, rather than Bcl-2 or Bcl-xL, may be the primary survival factor in AI-resistant ERα+ breast cancers." (PMID 29343814, 2018). "Moreover, RQ-PCR analysis revealed that the enhanced cytotoxic effect of As2O3 in the presence of melatonin is mediated, at least partly, through suppressing the expression of NF-κB anti-apoptotic target genes such as MCL-1, BCL-2, survivin, XIAP, and c-IAP1 in breast cancer cells." (PMID 31565647, 2018). "Targeted inhibition of Mcl-1 in ERα+ breast cancers using Mcl-1 siRNA encapsulated in polymeric nanoparticles (si-NPs) increased tumor cell killing in LTED-selected cells and in fulvestrant-treated cells, demonstrating that anti-estrogens prime ERα+ cells for targeted Mcl-1 inhibition." (PMID 29343814, 2018). "Although MCL-1 protein levels were comparable between TN and non-TN subtypes, MCL-1 high TN breast cancer patients showed the worst overall prognosis of all, P = 0.042 (Log-rank Mantel-Cox test) with only 64% survival at 10 years vs. 77% for MCL-1 low TN cases." (PMID 29339815, 2018). "However, preclinical and clinical testing of Mcl-1 blockade in combination with endocrine inhibition in ERα+ breast cancers is not fully explored." (PMID 29343814, 2018). "In addition, we show that silencing of Mcl-1 but not BOK reduced the long-term growth of breast cancer cells." (PMID 29156771, 2017). "There was a correlation between ERRF and MCL1 expression in breast cancer; and ectopic expression of ERRF decreased while the knockdown of ERRF increased the expression of MCL1 in breast cancer cells, suggesting that ERRF could directly downregulate MCL1 expression." (PMID 28415602, 2017). "Reintroducing FBXW7 activity or interfering MCL1 and PLK1 restores paclitaxel sensitivity in resistant cells and thus, targeting these substrates may be a valuable adjunct to paclitaxel for the treatment of breast cancer." (PMID 27409838, 2016). "Thus, we may conclude that MCL1 and PLK1 are contributors to the development of paclitaxel resistance in breast cancer cells." (PMID 27409838, 2016). "We show herein that the γ-secretase inhibitor, GSIXII, efficiently induces apoptosis in breast cancer cell lines by a process that relies on the induction of Noxa, a pro-apoptotic Bcl2-homology 3 domain (BH3)-only protein of the Bcl-2 family that functions as an inhibitor of antiapoptotic Mcl1." (PMID 22703841, 2012). "Importantly, MCL-1 was required for breast cancer stem cell function in vitro and this was also due to MCL-1’s canonical anti-apoptotic function since it could be ablated by deletion of BAX/BAK and targeted with MCL-1-specific BH3-mimetic drugs." (PMID 33785871, 2021).
breast carcinoma (continued). "To determine whether primary breast cancer could be targeted by a therapeutic strategy that reactivates MYC’s apoptotic potential via BH3 mimetics, we assessed the expression of MYC, BCL-2, BCL-XL, and MCL-1 using a tissue microarray (TMA) of 231 primary breast cancer samples." (PMID 30728358, 2019). "Importantly, xenograft experiments showed that therapeutic dosing with an MCL-1 inhibitor could retard TN breast cancer growth without any apparent adverse effects on the mice." (PMID 29339815, 2018). "To investigate whether pathways driving Mcl-1 expression are specifically active in HER2 overexpressing cancers, compared to other breast cancers, we analyzed the expression of 20 pro- and anti-apoptotic Bcl-2 family members from published gene-expression profiles of breast cancer patients." (PMID 21899728, 2011). "MCL1 copy number variations have been seen in triple negative, hormone receptor positive and ERBB2-positive breast cancer and have been correlated with both prognosis and resistance to various antitumor therapies." (PMID 38523186, 2024). "High levels of MCL-1 protein are found in breast cancers independent of the subtype, but BLBC has the highest MCL-1 expression, and up to 20% of BLBCs are characterized by genomic amplifications of MCL-1." (PMID 30720718, 2019). "Silencing of both Mcl-1 and BOK rescued the effect of Mcl-1 silencing on breast cancer cell growth, suggesting that BOK is important for attenuating cell growth in the absence of Mcl-1." (PMID 29156771, 2017). "In ERα negative breast cancer cell lines MDA MB 231 and SKBr3, the amount of Mcl-1 mRNA levels failed to increase." (PMID 24971890, 2014). "Immunoprecipitation analysis confirmed that the decline in Mcl-1 and Bcl-2 (data not shown) was only in CHX-treated normal mammary epithelial cells but not in the CHX-treated breast cancer cells." (PMID 21730980, 2011). "Addressing this key point, we set out to determine whether fully established tumours in an immune competent breast cancer model were dependent on MCL-1 and, if so, whether this was due to anti-apoptotic MCL-1 activity and/or its non-apoptotic functions." (PMID 33785871, 2021). "The Mcl-1 selective inhibitor VU661013 previously was shown to induce tumor cell killing in pre-clinical models of TNBC and acute myelogenous leukemia, but has not yet been tested in models of ER+ breast cancer." (PMID 31595181, 2019). "We found elevated Mcl-1 level in human colon cancer cell lines DLD1, LOVO, SW620, and HCT116; human ovarian cancer cell line SKOV3; and human lung cancer cell line H1299, but not in human breast cancer cell line MCF7 after they were treated with bortezomib." (PMID 22078414, 2011). "To further document the biological effects of MCL-1 targeting on bCAFs, we performed a differential gene expression (DGE) analysis on RNA-seq data from six different primary cultures of bCAF (derived from 3 triple negative and 3 luminal breast cancers) treated or not with S63845 (500 nM, 18 h)." (PMID 36104324, 2022). "As GSIXII induced the expression of proapoptotic Noxa, which inhibits the survival activity of Mcl-1, we inferred that its combination with the BH3 mimetic ABT-737, which targets Bcl-2 and Bcl-xL but not Mcl-1, might improve apoptosis induction in breast cancer cells." (PMID 22703841, 2012). "However, the expression levels of cyclin D1 and c-myc, but not those of Bcl-2 and Mcl-1, were increased upon PIAS3 overexpression in MCF7 cells, suggesting that the PIAS3-mediated effects on ER-positive breast cancer cells may be promoter-specific or ER-related." (PMID 26768588, 2016).
melanoma (244 papers, 2004 to 2026). A malignant, usually aggressive tumor composed of atypical, neoplastic melanocytes. "Elevated levels of MCL1 expression in melanoma patient tumors have been linked with worse responses to targeted or chemotherapies." (PMID 38459020, 2024). "An antiapoptotic protein that promotes resistance to numerous chemotherapeutic agents is encoded by the MCL1 gene, which is typically increased in melanoma as well as in many other kinds of tumors." (PMID 37026000, 2023). "MiR-339-5p has also been implicated in suppressing melanoma by targeting MCL1, which promotes chemoresistance." (PMID 36982154, 2023). "The effect of miR-1469 on MCL1 and sensitivity to apoptosis can thus be modulated by factors emanating from common melanoma mutations." (PMID 34469478, 2021). "In particular, activation of α5β1 integrin/PI3K/AKT signaling pathway and enhanced expression of the pro-survival myeloid cell leukemia 1 (Mcl-1) protein are associated with therapeutic escape and MAPKi resistance in melanoma." (PMID 34067929, 2021). "The HIF-1α-induced overexpression of antiapoptotic protein Mcl-1 (myeloid cell leukemia 1) was also observed in BRAF-mutated melanoma cells." (PMID 33918883, 2021). "The combined inhibition of ERK1/2 signaling together with MCL-1 induced synergistic apoptosis, inhibited the clonogenic survival of melanoma cells and caused regression of subcutaneous tumors in xenografts." (PMID 33308268, 2020). "Currently, it is considered that the extensively expressed of Mcl-1 protein in melanoma cells is associated with rapid tumor progression, poor prognosis and low chemosensitivity." (PMID 31432325, 2020). "The present study is the first that shows the capacity of specific Mcl-1 protein inhibitor – MIM1 to induce apoptosis in the amelanotic melanoma cells with BRAF V600E mutation and to intensify the proapoptotic properties of DTIC." (PMID 31432325, 2020). "In this regard, this function of BCL2L10 is similar to that of BCL2, Bcl-xL, and MCL1 since they are both abundantly expressed in melanoma and implicated in cisplatin resistance." (PMID 33396645, 2020). "The obtained results shown that amelanotic melanoma cells are susceptible to specific Mcl-1 inhibitor." (PMID 31432325, 2020). "Similar to the experiments with the melanoma cells, imatinib suppressed the association of MCL-1 with NOXA and concomitantly increased its association with BIM." (PMID 31727958, 2019). "To evaluate this possibility, we immunoprecipitated MCL-1 from drug-treated A375M melanoma cells and measured its association with NOXA by western blotting." (PMID 31727958, 2019). "Combinations of MCL-1 inhibitors with BRAF inhibitors also caused only minimal additional melanoma cell killing over each drug alone, whilst combinations with the proteasome inhibitor bortezomib was more effective in multiple cell lines." (PMID 31019203, 2019). "The expression levels of the identified target genes encoding CTGF, THBS1, STMN1, BCL9, RAC1 and MCL1 allowed discrimination between phenotypic groups of melanoma cell lines with high or low-invasive capacity, respectively." (PMID 30197759, 2018). "MCL-1 expression is associated with chemotherapeutic resistance and relapse in various cancers and its increased expression is correlated with melanoma progression." (PMID 27086916, 2017). "To further analyze effects of MCL1 in apoptosis caused by demethylzeylasteral, we treated melanoma cells overexpressing MCL1 and empty vector with 5 μM demethylzeylasteral, DMSO and empty vector were used as control." (PMID 29072681, 2017). "Since MCL-1 levels were greatly enhanced in ARF-deficient melanocytes as well in metastatic melanomas relative to wildtype, we investigated the possibility that ARF can regulate MCL-1 expression." (PMID 27846237, 2016). "In support of this notion BRAFV600 signaling has been reported to trigger apoptotic resistance in melanoma by selectively affecting the expression of the MCL-1 splice variant MCL-1L." (PMID 27846237, 2016).
melanoma (continued). "Associated with sensitization of melanoma cells to EGb761-induced apoptosis, knockdown of Mcl-1 promoted activation of Bax and Bak by EGb761 in Mel-RM cells." (PMID 25860257, 2015). "In our example, this set of steps identified the MCL1 gene from a melanoma-associated region as the most likely candidate." (PMID 25679399, 2015). "We then apply this strategy to a melanoma-associated region on chromosome 1 and identify MCL1 as a potential causative gene." (PMID 25679399, 2015). "Fittingly, MCL1 encodes a protein that regulates apoptosis and cellular differentiation, and hence is a strong candidate for involvement in melanoma susceptibility." (PMID 25679399, 2015). "For example, the expression of Mcl-1 increases with melanoma progression and is associated with poor patient prognosis." (PMID 25365078, 2014). "In melanoma, altered BCL-2, BCL-XL, and MCL-1 expression are associated with malignant transformation of melanocytic cells and progression to melanoma." (PMID 24983357, 2014). "The over expression of anti-apoptotic protein Mcl-1 has been associated with inferior survival, poor prognosis and chemoresistance of malignant melanoma." (PMID 24223823, 2013). "Among anti-apoptotic family, the overexpression of Mcl-1 has been shown to be associated with anoikis-, autophagy-resistance, and poor prognosis of various tumors including melanoma." (PMID 24223823, 2013). "In this report, we studied the effects of Maritoclax on Mcl-1 expression and associated apoptotic response in melanoma cells in 2- and 3-dimensional models." (PMID 24223823, 2013). "In support of this, expression of Mcl-1 has been shown to be the major cause of resistance of melanoma cells to apoptosis induced by ABT-737, which inhibits all anti-apoptotic Bcl-2 family proteins except Mcl-1 and A1." (PMID 24367627, 2013). "Because Mcl-1 is associated with melanoma progression, poor prognosis, and chemoresistance, we postulated that suppression of Mcl-1 would potentiate the apoptotic effects of ABT-737 in metastatic melanoma." (PMID 24223823, 2013). "The intrinsic sensitivity of melanoma cells to Mcl-1 and A1 loss is also supported by several studies that observed melanoma cell death that was associated with induction of the BH3-only protein Noxa." (PMID 22292048, 2012). "Interestingly, MCL-1 inhibitor can cause an increase in total MCL-1 protein level, which was observed in difficult-to-treat melanoma cells, and it was also found in the present study in ML-1 cells treated with S63845." (PMID 37108344, 2023). "Similarly, BRAF mutation driven melanoma exhibited resistance to BRAF inhibitors vemurafenib or dabrafenib due to overexpression of Mcl-1." (PMID 36045907, 2022). "Therefore, most likely secondary necrosis and not necroptosis is the basic mechanism leading to increased necrosis caused by TRAIL expression as well as by Mcl-1 silencing in AdV-TRAIL-infected melanoma cells." (PMID 34028599, 2021). "It has been shown that BRAF mutation in melanoma could increase MCL-1 expression, suggesting that activating BRAF mutations would confer resistance to apoptosis." (PMID 33917026, 2021). "Differences in the mutational profiles of melanoma cell lines may impact the observed effects of miR-1469 expression and its impact on MCL1 as a target gene." (PMID 34469478, 2021). "Furthermore, cleaved caspase 3 in WM-3246 cells treated with the three-drug combination but not with sirolimus alone, validating the induction of apoptosis by co-inhibition of BCL2 and MCL1 in sirolimus-sensitized NF1/PTEN-deficient human melanoma cells." (PMID 34331013, 2021). "The loss of cell viability and apoptosis induction in C32 melanoma cells after selective Mcl-1 inhibitor treatment, may be associated with overexpression of Mcl-1 protein in studied cells." (PMID 31432325, 2020).